MIR1283-1 (microRNA 1283-1)
Synonyms: hsa-mir-1283-1; MIRN1283-1; mir-1283-1
Gene: MicroRNA gene on chromosome 19 (53,688,481 to 53,688,567, forward strand). Ensembl gene ENSG00000221421.
Gene Ontology:
Biological process: miRNA-mediated post-transcriptional gene silencing